PHLPP2 (PH domain and leucine rich repeat protein phosphatase 2)
Diseases named in the same sentence as PHLPP2 in open-access papers (continued):
Sharing a sentence is not in itself a finding about the gene and the disease.
colon carcinoma (12 papers, 2015 to 2025). "LINC00402 and other lncRNAs enhance PHLPP2 expression by competing with the endogenous RNA network and exerting repression in colon cancer pathogenesis." (PMID 36147735, 2022). "In colon cancer, LINC00402 competitively binds miR-141 and miR-424 as the ceRNA of PHLPP2, and LINC00402 has also been confirmed to be associated with metastatic melanoma." (PMID 34324544, 2021). "In comparison to the adjacent tissues, expression of PHLPP2 was significantly decreased while miR-141 and miR-424 exhibited increased expression in colon cancer tissues." (PMID 32633726, 2020). "The upregulation of LINC00402, LINC00461, and SFTA1P was verified to enhance the suppressive effects of PHLPP2 in the pathogenesis of colon cancer." (PMID 32633726, 2020). "The results showed that overexpression of LINC00402, LINC00402, and SFTA1P enhanced the suppression of PHLPP2 on EMT in colon cancer cells." (PMID 32633726, 2020). "RT-qPCR was applied to determine the expression of PHLPP2 mRNA, miR-141, and miR-424 in both the colon cancer and adjacent tissues." (PMID 32633726, 2020). "The PHLPP2 was found to be localized in the nucleus and cytoplasm of cells whereas the expression of PHLPP2 in the colon cancer tissues was notably lowered than that in adjacent tissues." (PMID 32633726, 2020). "Immunohistochemistry methods were applied to explore the expression of PHLPP2 in the colon cancer tissues and adjacent tissues." (PMID 32633726, 2020). "This study aimed to unravel the possible involvement of long noncoding RNAs (lncRNAs) and microRNAs (miRNAs) regulating PHLPP2 in colon cancer." (PMID 32633726, 2020). "In consent with our present study, a tumor suppressor in colon cancer, PHLPP2 has been reported to undergo progressive depletion in colon cancer cells." (PMID 32633726, 2020). "In an attempt to validate the inhibitory role of PHLPP2 in colon cancer, tumor xenografts in nude mice were applied to evaluate the effect of PHLPP2 on tumor growth." (PMID 32633726, 2020). "Taken together, these findings demonstrated the regulatory role of PHLPP2 in cellular behaviors of colon cancer cells." (PMID 32633726, 2020). "Among the five colon cancer cell lines, HT-29 exhibited the lowest PHLPP2 mRNA and protein levels, therefore, the HT-29 cell line was selected as the appropriate cell line for subsequent trials." (PMID 32633726, 2020). "Recently, homologous pleckstrin-homology (PH)-domain leucine-rich-repeat protein phosphatases (PHLPP2) has been reported as a tumor suppressor in colon cancer." (PMID 32633726, 2020). "The KEGG analysis revealed correlations of AJUBA, CLDN1, and PHLPP2 with signaling pathways related to the occurrence and progression of colon cancer." (PMID 32633726, 2020). "The regulatory effects in the ADAMTS9‐AS2/miR‐32/PHLPP2 axis was proved by knockdown or overexpression of ADAMTS9‐AS2 in colon cancer cell lines." (PMID 31144439, 2019). "Overexpression of ADAMTS9‐AS2 in colon cancer cell lines significantly inhibited the miR‐32 expression and promoted PHLPP2 expression, while ADAMTS9‐AS2 knockdown had the opposite effects." (PMID 31144439, 2019). "Similarly, USP46‐mediated PHLPP1 and PHLPP2 stabilization decreases cell proliferation and tumorigenesis in colon cancer cells." (PMID 41000374, 2025). "The overexpression of miR-141 or miR-424 could suppress the inhibition effect of PHLPP2 on development of colon cancer." (PMID 32633726, 2020). "Our analysis indicated that PHLPP2 might be the target of both miR-141 and miR-424, which have been reported to increase in colon cancer." (PMID 32633726, 2020).
colon carcinoma (continued). "PHLPP2 upregulation and miR-141 and miR-424 downregulation suppressed the colon cancer cell proliferation, migration, invasion, and epithelial-mesenchymal transition, and promote cell apoptosis, which also resulted in suppression of tumor metastasis and formation." (PMID 32633726, 2020). "PHLPP2, a target of miR-141 and miR-424, was downregulated in colon cancer." (PMID 32633726, 2020). "Moreover, our results from colon cancer also confirmed that expression of PHLPP2 was decreased in colon cancer, while the expression of miR-141 and miR-424 was increased." (PMID 32633726, 2020). "PHLPP2 was revealed to be downregulated in colon cancer, which was a target of miR-141 and miR-424." (PMID 32633726, 2020). "Moreover, our study also identified PHLPP2 as a protective candidate gene in colon cancer by DEGs whilst our in vivo and in vitro results confirmed the tumor-suppressive role of PHLPP2 in colon cancer." (PMID 32633726, 2020). "Moreover, the TCGA database revealed that miR-141, miR-424, and miR-32 were upregulated in colon cancer whereas the miRDB, miRTarBase, and TargetScan websites indicated that miR-141, miR-424, and miR-32 efficiently bound to PHLPP2." (PMID 32633726, 2020). "Similarly, in colon cancer cells hypoxia reduces USP46 mRNA and protein levels and, therefore, diminishes USP46’s stabilizing effect on the tumor suppressors PHLPP1 and PHLPP2, conferring to the colon cancer cells an increased paclitaxel resistance." (PMID 27014628, 2016). "Hence, our result confirmed that both miR-141 and miR-424 could bind to PHLPP2 mRNA and inhibit the PHLPP2 tumor-suppressive effect in colon cancer." (PMID 32633726, 2020). "Ten RNAs were finally obtained related to colon cancer, which were hsa-miR-2682-5p, hsa-miR-1277-3p, ANGPTL1, SLC22A18AS, FENDRR, PHLPP2, hsa-miR-302a-5p, APCDD1, MEX3A and hsa-miR-509-3-5p." (PMID 36101384, 2022). "The TCGA results indicated that SPIB, KRT24, PHLPP2, PLP1, BEST4, CA7, and C11orf86 were all downregulated, while KRT80, SLC39A10, AJUBA, FOXQ1, and CLDN1 exhibited upregulated levels in colon cancer." (PMID 32633726, 2020). "Our results indicated that compared with the CCD 841 CoN cell line, the human colon cancer cell lines (HT-29, SW480, Lovo, HCT-116 and SW620) presented descended expressions of PHLPP2 mRNA and protein (both p < 0.05)." (PMID 32633726, 2020). "Conjointly, our results demonstrated the suppressive effects of PHLPP2 in colon cancer and proved that LINC00402, LINC00461, and SFTA1P acted as ceRNAs of PHLPP2 by competitive binding to miR-141 and miR-424." (PMID 32633726, 2020). "Since the PHLPP2 expression was highest in the SW620 colon cancer cell line among the colon cancer cell lines, PHLPP2 was then upregulated in the SW620 cell line to further investigate the biological function of PHLPP2 in colon cancer cells followed by cellular behavior evaluation." (PMID 32633726, 2020). "Notably, overexpression of PHLPP2, as well as the inhibition of miR-141 or miR-424 could inhibit the proliferation, migration, invasion, and EMT of colon cancer cells by inhibiting the activation of the Akt3-p27 pathway." (PMID 32633726, 2020).
lung cancer (9 papers, 2013 to 2023). A malignant neoplasm involving the lung. "The expressions of PTEN and PHLPP2 were inhibited after miR-205 was overexpressed in lung cancer cell lines." (PMID 37576883, 2023). "In conclusion, our data highlight the importance of TRIM46/PHLPP2/AKT signaling in lung cancer and provide new insights into therapeutic strategies for lung cancer." (PMID 35354796, 2022). "In contrast, miR-205 in non–small cell lung cancer targeted PHLPP2 and PTEN and enhanced AKT signaling, resulting in cancer development." (PMID 33167959, 2020). "As this study of lung cancer involved a limited number of patients, it is essential to determine the tumor suppressive role of PHLPP2 as a promising prognostic biomarker based on investigations of larger samples." (PMID 31571378, 2019). "The Cancer Genome Atlas (TCGA) and Gene Expression Omnibus (GEO) databases including data on 1383 non‐small cell lung cancer (NSCLC) patients were used to determine PHLPP2 expression." (PMID 31571378, 2019). "The findings highlighted the importance of TRIM46/PHLPP2/AKT signaling which might be helpful in developing new drugs for lung cancer treatments." (PMID 35354796, 2022). "Whether PHLPP2 is regulated in a similar manner as PHLPP1 with dysregulations in its expression in lung cancer can be examined in the future." (PMID 23724143, 2013). "At the same time, we elucidated related proteins that directly act on PHLPPs in lung cancer, including USP46 through the effect of PHLPP1 on AKT, and the effect of miR-205 on PHLPP2 and miR-190 on PHLPP1." (PMID 37576883, 2023). "Several previous studies have confirmed the cancer-promoting role of miR-205-5p in lung cancer, targeting genes such as PTEN, PHLPP2, and SMAD4." (PMID 37670265, 2023). "In lung cancer, TRIM46 activates AKT/HK2 signaling by modifying PHLPP2 ubiquitination to promote glycolysis and chemoresistance, which reflects the importance of TRIM46/PHLPP2/AKT signaling in lung cancer and provides a new strategy for lung cancer treatment." (PMID 36249749, 2022). "However, PHLPP2 has not been fully researched as a putative clinical prognostic biomarker of lung cancer." (PMID 31571378, 2019).
prostate carcinoma (7 papers, 2014 to 2025). A carcinoma that arises from epithelial cells of the prostate gland. "A loss of PHLPP2 is associated with progression of pancreatic and prostatic cancer." (PMID 32612536, 2020). "A number of genetic alterations in genes that encode AKT regulators have been linked to prostate cancer, including kinases (e.g., PDK1), binding proteins (e.g., FKBP5), and phosphatases (e.g., PHLPP1, PHLPP2, and PP2A)." (PMID 32630372, 2020). "PHLPP1 and PHLPP2 deep deletion occurs in up to 3.9% and 6.5% of patients with prostate cancer respectively, which could potentially sustain AKT-signaling." (PMID 32630372, 2020). "Consequently, in PHLPP2-positive MYC-driven advanced prostate cancer, it has been suggested that PHLPP2 may present a valuable therapeutic target." (PMID 32630372, 2020).
endometrial cancer (5 papers, 2020 to 2024). Primary or metastatic malignant neoplasm involving the endometrium (mucous membrane that lines the endometrial cavity). "In endometrial cancer, reduced METTL3 expression leads to a decrease in m6A modification on PHLPP2 mRNA, resulting in attenuated YTHDF1-mediated translation of PHLPP2, which in turn caused de-repression of the AKT pathway and promotes tumor progression." (PMID 36830614, 2023). "Expression levels of PHLPP1 and PHLPP2 mRNAs in samples of endometrial cancers and normal endometrial tissues were also analysed by RT‐PCR and correlated with clinical and pathomorphological data." (PMID 31863623, 2020). "Likewise, in endometrial cancer, METTL3 contributes to the decay of transcripts such as PHLPP2 and mTORC2 via YTHDF2, inhibiting cancer cell proliferation." (PMID 38966069, 2024). "Reductions in m6A methylation decreased the negative AKT regulator PHLPP2 expression and increased the positive AKT regulator mTORC2 expression, which contributed to increased proliferation and tumorigenicity of endometrial cancer cells through the activation of AKT pathway." (PMID 34906165, 2021).
gastric cancer (5 papers, 2017 to 2024). A primary or metastatic malignant neoplasm involving the stomach. "It has been shown that overexpression of miR-27a was associated with high cell proliferation and metastasis in gastric cancer cells through mediating suppression of PH domain and leucine-rich repeat protein phosphatase 2 (PHLPP2) leading to stimulation of the AKT/GSK3B pathway." (PMID 34582667, 2021). "In gastric cancer, suppression of PHLPP2 leads to up-regulation of pAKT and the acceleration of EMT20." (PMID 38589525, 2024). "The result of PHLPP2 expression in gastric cancer tissues by qRT-PCR showed that PHLPP2 mRNA levels were reduced in GC tissues compared to adjacent normal tissues." (PMID 28327189, 2017). "In summary, our current study demonstrated that miR-27a possessed tumor inducing effects on gastric cancer through the novel target PHLPP2." (PMID 28327189, 2017). "Furthermore, we found PH domain and leucine-rich repeat protein phosphatase 2 (PHLPP2) to be a new target of miR-27a, and downregulation of PHLPP2 could rescue the effect of anti-miR-27a in gastric cancer cells." (PMID 28327189, 2017). "Here we found that miR-27a promoted gastric cancer cells metastasis by interacting PHLPP2, which is novel finding and has not been reported previously to the best of our knowledge." (PMID 28327189, 2017).
hepatocellular carcinoma (5 papers, 2015 to 2025). A malignant tumor that arises from hepatocytes. "F‐Box Protein 32 (FBXO32) is markedly overexpressed in hepatocellular carcinoma and facilitates tumor progression by activating the PI3K–AKT signaling pathway via PHLPP2 degradation, underscoring its potential as a promising therapeutic target." (PMID 41000374, 2025).
pancreatic cancer (5 papers, 2016 to 2025). "For instance, circ-ANAPC7 suppresses cell proliferation via the PHLPP2-AKT-TGF-β axis in pancreatic cancer." (PMID 41214390, 2025). "Cigarette smoke promotes the development and progression of pancreatic cancer via the METTL3/miR-25-3p/PHLPP2/AKT regulatory axis." (PMID 35155557, 2022). "In short, smoking plays a role in the development and progression of pancreatic cancer through the METTL3/miR-25-3p/PHLPP2/AKT regulatory axis." (PMID 35155557, 2022). "We have interrogated the mRNA expression of PHLPP in several gene expression databases and found that the expression of PHLPP1 is significantly decreased in pancreatic tumor samples compared to normal samples whereas PHLPP2 mRNA expression is less affected." (PMID 26760962, 2016). "According to a recent report, circ‐ANAPC7 regulates the CREB–miR‐373–PHLPP2 feed‐forward loop through the PHLPP2–AKT–TGF‐β signaling axis, preventing pancreatic cancer muscle atrophy and tumor progression." (PMID 39239069, 2024). "To determine if PHLPP serves as a tumor suppressor in human pancreatic cancer, we established stable cell lines overexpressing PHLPP1 or PHLPP2 in Panc-1 cells, which express very low levels of endogenous PHLPPs." (PMID 26760962, 2016). "Moreover, miR-25-3p inhibits PHLPP2 and activates oncogenic AKT-p70S6K signaling, and promotes the occurrence and progression of pancreatic cancer." (PMID 36212476, 2022).
colitis (4 papers, 2021 to 2022). Inflammation of the colon. "Recent studies have also found that the loss of PHLPP2 expression contributes to epithelial pyroptosis facilitating rapid progression of colitis." (PMID 35308140, 2022). "PHLPP2 might be a promising candidate therapeutic target for colitis, and the up-expression of PHLPP2 could inhibit the NF-κB signaling pathway to alleviate colonic inflammatory response." (PMID 35893911, 2022). "Furthermore, we found that PHLPP2−/− mice developed hypersensitivity to dextran sulfate sodium (DSS) treatment toward colitis showing activated NF-κB signaling and dramatically induced expressions of caspase-1 P20, Gasdermin N, IL-18, and IL-1β." (PMID 34394827, 2021). "Therefore, it suggested that PHLPP2 depletion led to colonic epithelial pyroptosis and promoted colitis progression." (PMID 34394827, 2021). "Therefore, PHLPP2−/− mice developed hypersensitivity to DSS treatment toward colitis, which might be mainly attributed to NF-κB signaling activation and the subsequent induction of IEC pyroptosis." (PMID 34394827, 2021). "In conclusion, we, for the first time, showed that downexpression of PHLPP2 directly activated the NF-κB signaling and promoted the IEC pyroptosis, leading to the progression of colitis in UC." (PMID 34394827, 2021).
glioblastoma (4 papers, 2022 to 2025). The most malignant astrocytic tumor (WHO grade IV). "The reduced expression of PHLPP2 is significantly associated with unfavorable prognosis in glioblastoma patients." (PMID 39407269, 2024). "For example, in glioblastoma microenvironments, miR‐25‐3p targets PHLPP2 to alleviate AKT dephosphorylation inhibition, activating the AKT‐mTORC1 axis to drive M2 polarization." (PMID 41360672, 2025). "This regulatory mode exhibits spatiotemporal heterogeneity, akin to the miR‐25‐3p/PHLPP2 axis‐driven AKT‐mTORC1 activation in hypoxic glioblastoma microenvironments." (PMID 41360672, 2025). "PHLPP2 phosphatase plays an inhibitory role for glioblastoma cell progression by dephosphorylating and inactivating Akt." (PMID 35654777, 2022).
lung adenocarcinoma (4 papers, 2017 to 2025). A carcinoma that arises from the lung and is characterized by the presence of malignant glandular epithelial cells. "High expression levels of PHLPP1 and PHLPP2 were detected in 69.3% and 61.3%, respectively, of patients with lung adenocarcinoma." (PMID 28938613, 2017). "Furthermore, TRIM46 amplification is associated with decreased PHLPP2 levels, increasing p‐AKT levels and promoting glycolysis in lung adenocarcinoma." (PMID 41000374, 2025).
Obesity (4 papers, 2016 to 2025). Accumulation of substantial excess body fat. "However, both the studies negate the involvement of PHLPP2 in insulin resistance associated with obesity or diabetes." (PMID 36376971, 2022). "For example, MACROD2, PHLPP2, CYP2E1, and STT3B are associated with obesity in the body, play a role in fat metabolism, and there is a close link between them and growth traits." (PMID 40244387, 2025). "Recently, only one study reported higher adipocyte PHLPP2 levels in obese mice as compared to lean mice and a possible inter-organ cross-talk with the liver, indicating a role of PHLPP2 in obesity-related metabolic disorders." (PMID 36376971, 2022). "In the liver, aged and obese mice also display lower PHLPP2 protein levels, affecting Akt signaling and inducing obesity-induced insulin resistance." (PMID 36376971, 2022). "Free Raptor levels in liver decline with age and in obesity; restoration of free Raptor levels reduces liver triglyceride content, through reduced β-TrCP-mediated degradation of the Akt phosphatase, PHLPP2." (PMID 26743335, 2016). "Free Raptor levels decline with aging and obesity—consistently, despite unchanged hepatic Phlpp2 gene expression, we observed lower PHLPP2 protein levels with aging and in dietary or genetic models of obesity." (PMID 26743335, 2016). "In addition, several genes were identified that are associated with obesity and play roles in lipid metabolism, including MACROD2, PHLPP2, CYP2E1, and STT3B." (PMID 40244387, 2025). "Overall, these data implicate an adipocyte PHLPP2-HSL-PPARα signaling axis to regulate systemic glucose and lipid homeostasis, and suggest that excess adipocyte PHLPP2 explains decreased adiponectin secretion and downstream metabolic consequence in obesity." (PMID 33758172, 2021). "Consistently, mild hepatic PHLPP2 overexpression reduced lipogenic gene expression and obesity-induced triglyceride accumulation, without affecting glucose tolerance." (PMID 26743335, 2016).
ovarian carcinoma (4 papers, 2015 to 2024). A malignant neoplasm originating from the surface ovarian epithelium. "For example, it is reported that miR-760 was strongly overexpressed in ovarian cancer and miR-760 upregulation drastically promoted ovarian cancer cell proliferation by inhibiting the expression of PHLPP2." (PMID 29661228, 2018).